MITF (melanocyte inducing transcription factor)
Diseases named in the same sentence as MITF in open-access papers (continued):
Sharing a sentence is not in itself a finding about the gene and the disease.
melanoma (continued). "Overall, in BRAF mutant/MITF‐positive melanoma cells, a BRAF/BRN2 rheostat appears to control MITF basal expression levels." (PMID 25818589, 2015). "WNT5A suppresses MITF and its downstream effector MART-1 (melanoma antigen recognized by T cells-1), which has also been positively correlated with melanoma cell migration." (PMID 26393652, 2015). "TGFβ can also suppress MITF expression directly through GLI2, suggesting that reduced MITF expression is relevant for the execution of TGFβ signalling in melanoma." (PMID 25818589, 2015). "Despite the fact that YY1 ChIP-seq was performed in a distinct melanoma line, we identified 2853 sites where YY1 co-localized with MITF and 3060 SOX10-YY1 co-occupied sites." (PMID 25803486, 2015). "In distinct areas of melanoma biopsies, BRN2 and MITF expression levels are found inversely correlated." (PMID 25818589, 2015). "On the other hand, treatment of non‐resistant melanoma cells with TGFβ suppresses PAX3 and MITF expression and sensitizes melanoma cells to MEK inhibition." (PMID 25818589, 2015). "Among these genes MITF, WNT/beta Catenin, SOX9, SOX2, PAX3, RANK/RANKL are important in melanocyte differentiation and melanoma." (PMID 25612317, 2015). "This is in concordance with the phenotype switching model, where highly invasive melanoma cells show high BRN2 expression and proliferative melanoma cells show an MITF-regulated gene expression profile; thus BRN2 and MITF act mutually exclusively." (PMID 25880082, 2015). "MITF expression in melanoma is heterogeneous, and recent findings highlight the relevance of this heterogeneity for the response of melanoma to MAPK pathway targeting drugs, as well as for MITF's role in melanoma progression." (PMID 25818589, 2015). "This allows BRAF to assume control over the regulation of MITF expression, and BRN2 depletion abolishes the ability of BRAFV600E to activate the MITF promoter in human melanoma cells." (PMID 25818589, 2015). "We show here that BPTF acts as a cofactor for MITF in regulating critical cell cycle, invasion, motility and apoptosis genes thus providing a molecular mechanism by which BPTF promotes melanoma growth and progression." (PMID 26440048, 2015). "PRMT5 expression has been found to be increased in melanoma, and siRNA-mediated depletion of PRMT5 resulted in a substantial decrease in the level of MITF protein indicating a positive regulatory effect." (PMID 25433395, 2015). "Previous studies revealed that the BRAF mutation hyper-activated the MAPK signaling pathway and led to MITF promotion, whereas TGFB1 was reported to be down-regulated in multiple cancers, including melanoma." (PMID 25890285, 2015). "Immunohistochemical analyses of MITF and WNT5A, markers of the proliferative and invasive phenotype, respectively, of human primary and metastatic melanomas displayed an anti-correlative staining pattern confirming that these phenotypes exist in vivo." (PMID 25885555, 2015). "This may explain a variable MITF expression across melanoma specimens but also between different areas of individual tumor samples reflecting both inter-tumoral heterogeneity and diversity of melanoma cell subpopulations comprising a tumor mass [123, 124; for review 125]." (PMID 25433395, 2015). "Xenografted tumors displayed expression of CD271 as well as melanoma differentiation markers TYR and MITF." (PMID 24799129, 2014). "MITF and PAX3 bind directly to the MET promoter; coexpression of these three proteins is found in melanoma biopsies." (PMID 24743024, 2014). "SOX10, PAX3, and MITF participate in regulation of MET (HGF receptor), which is expressed at high levels in human melanoma." (PMID 24743024, 2014). "Two primary melanoma cultures, DMBC8 and DMBC12, showing the highest difference in MITF expression were chosen." (PMID 24595456, 2014). "We also examined the TYR activity and melanin content in B16 melanoma cells, as well as the expression of TYR, TRP-1, TRP-2 and MITF in B16 cells." (PMID 24884952, 2014).
melanoma (continued). "Among these genes, the transcription factor MITF, the pigmentation enzyme TYR, and MLANA and GPR143 that are involved in melanosome biogenesis, are important players in melanoma." (PMID 25207815, 2014). "Using melanoma cell lines and melanoma cells freshly isolated from patient biopsies, we investigated the relationship between ABCB5+, CD271+ and low-MITF, expressing populations that were reported to display melanoma initiating cell properties." (PMID 25105565, 2014). "Next, we searched for CNAs in genes known to be affected by CNAs in melanoma (BRAF, KIT, MITF, CCND1, CDK4, PTEN, CDKN2A and AKT3)." (PMID 24399611, 2014). "In mutant BRAF-harboring melanoma cells that are resistant to MAPK inhibitors, MITF is downregulated whereas Axl and NFκB signaling is upregulated." (PMID 25344858, 2014). "For now, panobinostat/ LBH589 (HDAC inhibitor) is in early clinical testing in melanoma (NCT01065467), and also involves examining the effect of panobinostat on MITF expression." (PMID 24743024, 2014). "MITF drives most of the melanocytic markers, and interestingly, DYRK1A mRNA is downregulated in melanoma cell lines." (PMID 24901999, 2014). "Through in-depth study of initial biopsy with immunohistochemistry for S-100, HMB-45, MART-1, and MITF, along with karyotyping and FISH analysis for EWS gene rearrangement, the diagnosis of amelanotic malignant melanoma was confirmed." (PMID 24274261, 2013). "A recent study showed that CDK2 expression was regulated in melanoma cells by the melanocyte specific transcription factor MITF, and that CDK2 knockdown significantly reduced melanoma growth." (PMID 23527225, 2013). "Nevertheless, it should be noted that several known MITF target genes such as MLANA, RAB27a or SLC24A5 were weakly but significantly downregulated in all three melanoma cells, in accordance with the observations of a reduced MITF expression." (PMID 24344100, 2013). "We found that in a panel of melanoma cell lines, ML-IAP expression was correlated with coexpression of both MITF and BRG1." (PMID 23480510, 2013). "To determine the correlation between PARP-1 expression and disease progression in human melanoma, we used IHC to analyze the levels of vimentin, PARP-1, Snail1, E-cadherin and MITF in nodular and metastatic melanoma frozen biopsies." (PMID 23785295, 2013). "The recent report showed that gallic acid suppressed melanogenesis in melanoma cells through inhibition of tyrosinase, TRP-1, Dct, and MITF." (PMID 24129178, 2013). "A375 melanoma cells express high levels of BRG1, but low levels of MITF and undetectable levels of ML-IAP, whereas SK-MEL-5 cells express high levels of MITF, but virtually undetectable levels of BRG1 and undetectable levels of ML-IAP." (PMID 23480510, 2013). "As an activator of ML-IAP expression in melanoma cells, BRG1 diverges from its well-known role in tumor suppression and promotes a critical survival pathway by cooperating with MITF." (PMID 23480510, 2013). "Concerning the role of MITF, we have initial data indicating reduced invasion and migration of IGR37 melanoma cells following MITF silencing by siRNAs." (PMID 24039954, 2013). "We investigated the interaction between genes within our 200-gene signature with the four known melanoma ‘driver’ genes (i.e., NRAS, BRAF, MITF and cKIT)." (PMID 23638386, 2013). "It has been previously shown that MITF is critical for maintaining the expression of CDK2 in melanoma cells, and that that levels of both CDK2 and MITF predict responses to the CDK inhibitor roscotivine." (PMID 23527225, 2013). "Prolonged depletion of YY1 led to decreased cell numbers in both YY1 knockdown MALME-3M melanoma cells and human foreskin primary melanocytes (HFM), similar to MITF knockdown." (PMID 22570637, 2012). "In melanoma cells, the POU domain bearing brain-2/POU class 3 homeobox transcription factor 2 (Brn2) repressed MITF expression." (PMID 22912767, 2012).
melanoma (continued). "Furthermore, MITF may have a major role in the propensity of melanoma to become metastatic." (PMID 22927992, 2012). "It has been reported that MITF-depleted senescent cells activated the DNA damage response, whereas silencing of DEK increased sensitivity of melanoma cells to the DNA damaging agents." (PMID 23249808, 2012). "MITF is sometimes amplified in certain subsets of melanoma cells and cooperates with mutant BRAF to regulate melanoma proliferation." (PMID 23006971, 2012). "Disruptions in the MITF cascade, such as levels of the MITF regulator, BRAF, and the MITF target, c-Met, can lead to melanoma progression." (PMID 22848417, 2012). "A tight correlation has been observed between MITF and CDK2 expression levels in primary melanoma specimens and several melanoma cell lines." (PMID 22848417, 2012). "Here, CTCs were enriched (∼400X) from blood of melanoma patients using a simple centrifugation device (OncoQuick), and 4 melanocyte target RNAs (TYR, MLANA, MITF, and MIF) were quantified using QPCR." (PMID 22829910, 2012). "Treatment with SPC suppressed MITF promoter activity induced by α-MSH in B16 melanoma cells, indicating that SPC blocks the transcription of MITF." (PMID 21838918, 2011). "In melanoma, many studies have focussed on the copy number and gene expression levels of the BRAF, PTEN and MITF genes, but little has been done to identify new genes using these parameters at the genome-wide scale." (PMID 21494657, 2011). "In contrast, 6/12 melanoma lines revealed decrease in MITF expression, of which 5 also shown decrease in SOX10 expression, pointing to positive regulation of SOX10 and MITF in these melanoma cells." (PMID 21203491, 2010). "In order to validate PAX3 expression in naevi and melanomas as well as to confirm that PAX3-positive cells in normal skin are in fact melanocytes, co-staining of PAX3 and MITF was assessed by immunofluorescence." (PMID 20421967, 2010). "Since MiTF is often amplified in melanoma, GPNMB expression in melanoma cells is likely to be a result of elevated MiTF transcriptional activity." (PMID 21209915, 2010). "Pull-down assays using biotin-tagged MITF promoter sequences harboring the CRE identified ATF2 and CREB as CRE-bound proteins in MeWo melanoma cells." (PMID 21203491, 2010). "In all, these findings provide genetic evidence for the role of ATF2 in melanoma development and indicate an ATF2 function in fine-tuning MITF expression, which is central to understanding MITF control at the early phases of melanocyte transformation." (PMID 21203491, 2010). "MITF downregulation by ATF2 was confirmed in the skin of Atf2−/− mice, in primary human melanocytes, and in 50% of human melanoma cell lines." (PMID 21203491, 2010). "Three melanoma cell lines (A375, 1205Lu and WM3211) which accumulated undetectable MiTF protein showed higher cell death (19% to 26%) as compared to three MiTF-positive melanoma cell lines (Malme-3 M, SK-Mel-28 and c83-2C) (4% to 10%)." (PMID 20701798, 2010). "Because p16INK4A is often lost in melanoma cells, we examined accumulation of CDK inhibitors p21WAF1/CIP1 and p27KIP1, both of which are downstream of MiTF." (PMID 20701798, 2010). "MiTF also controls the expression of Tbx2 and CDK2, which are involved in melanoma proliferation and suppression of senescence, in addition to anti-apoptotic genes such as Bcl2 and ML-IAP." (PMID 20174581, 2010). "The first class comprised four of the six melanoma cultures (1205Lu, WM35, WM793 and WM1361), in which MITF expression was elevated 3–6-fold following inhibition of ATF2 expression." (PMID 21203491, 2010). "MITF has been shown to be superior to the S100 and HMB-45 combination in both sensitivity and specificity in the diagnosis of melanoma." (PMID 20163701, 2010). "In melanoma cells, activated BRAF suppresses MITF protein levels through ERK-mediated phosphorylation and degradation." (PMID 19828018, 2009).
melanoma (continued). "This ensures that the levels of MITF are optimal for tumour progression and suggests one reason for why BRAF is such a potent oncogene in human melanoma." (PMID 18628967, 2008). "In metastases of melanoma to lymph nodes, lung and heart, RACK1 protein was abundant on MITF+ cells." (PMID 18442364, 2008). "In oral/digit melanomas, positive relationships were observed between larger tumors (p = 0.007), higher mitotic index, and the absence of MiTF expression." (PMID 41604042, 2026). "Additionally, SM can be transformed into sphingosylphosphorylcholine (SPC), a bioactive lipid shown to drive melanoma progression by activating key signaling pathways, including ERK, MITF, and Akt/mTOR." (PMID 41596686, 2026). "Here, we investigate the role of TFEB and TFE3 in cells that also express MITF to better understand the potential of these related transcription factors to exhibit distinct and non-redundant roles in gene expression and melanoma progression." (PMID 41275493, 2025). "Interestingly, in cases where DDIT4L expression was detectable in TCGA primary melanomas, DDIT4L correlated with MITF." (PMID 40918647, 2025). "At the protein level, MITF did not significantly change in either melanoma cell line but was reduced in melanocytes." (PMID 41465475, 2025). "In a TTD model for melanocytes—the progenitor cells of melanoma—the MITF gene signature was also increased, but here without affecting REDD2 expression." (PMID 40918647, 2025). "This led us to investigate whether the newly identified BRD4–MITF interaction in melanoma cells is mediated by the BD of BRD4 and acetylated MITF." (PMID 40809945, 2025). "In addition, fisetin significantly decreased mRNA levels and suppressed the expression of MITF, tyrosinase, TRP-1, TRP-2, and PMEL in both melanoma and α-MSH-stimulated melanoma cells." (PMID 41373883, 2025). "While MITF has been shown to antagonize pro-inflammatory responses through inhibition of NF-κB and AP-1 in melanoma, we did not observe a reduction in MITF and PGC-1α transcript in MeWo cells treated with the RSK/PLK1 inhibitor BI-D1870." (PMID 39658088, 2025). "Theophylline, a purine alkaloid and the main ingredient in tea plants, has been found to improve the protein expression levels of MITF, TYR, TRP‐1 and β‐catenin and promote the phosphorylation of ERK and GSK3β to increase melanin content in B16F10 murine melanoma cells." (PMID 40457938, 2025). "Analyses of several published melanoma signatures showed increased expression of invasion-related pathways (“MITF targets”, “Invasion” and “MSC” melanoma signatures) in GFP+ cells, and of proliferation- and melanocyte-associated pathways (“Mitotic” and “Pigmentation” signatures) in GFP− cells." (PMID 40528051, 2025). "Additionally, 2,6′-DMC exhibited a significant inhibition of α-melanocyte-stimulating hormone (α-MSH)-induced melanin synthesis in B16F10 melanoma cells by downregulating tyrosinase, TRP-1, TRP-2, and MITF expression." (PMID 39996806, 2025). "As observed in our case, S100-negative melanomas frequently retain SOX10 and MITF expression." (PMID 41458594, 2025). "□ Melanoma: Common markers include S-100 protein, SOX-10, Melan A, HMB45, tyrosinase, and MITF." (PMID 40308487, 2025). "Smooth Muscle Actin (SMA), an antigen expressed by certain melanoma cells (NKI-C3), microphthalmia-associated transcription factor (MITF), and Melan-A were negative." (PMID 40988822, 2025). "Hence, our study explored the effects of SPEF on MITF, TRP-1, TRP-2, and tyrosinase expressions in α-MSH-treated melanoma cells." (PMID 40003988, 2025). "MITF itself acts as a tumour suppressor in melanomas by inhibiting EMT and cell invasion, suggesting that the effect of FOXQ1 on melanoma progression is controlled by multiple converging mechanism that may not occur in other cell types." (PMID 39777582, 2025).
melanoma (continued). "MITF has been identified as a regulator of normal melanocyte development and differentiation and has demonstrated the ability to inhibit invasion and EMT in melanoma." (PMID 39858044, 2025). "The transcription factor MITF plays a non-transcriptional role in suppressing the DNA damage response in melanoma cells." (PMID 40588654, 2025). "In an in vitro study using B16-F10 melanoma cells, α-MSH was found to induce a dose-dependent increase in melanin synthesis, tyrosinase activity, and the expression of key melanogenic proteins, including TRP-1, TRP-2, and MITF." (PMID 40076896, 2025). "Additionally, we investigated the gene regulatory interactions in melanoma, identifying crucial network motifs that involve SOX10, MITF, and miRNAs." (PMID 40458894, 2025). "AXL, CDK6, and Fascin did not specifically correlate with the stage of the melanomas from which these cell lines were derived, while MITF expression negatively correlated with FRA1 and its targets." (PMID 41286309, 2025). "In these cells, we identified several known melanoma PAX3 targets, including MITF and BRN2/POU3F2." (PMID 40428399, 2025). "However, when comparing distinct DIFF populations of melanocytic cells, including melanoma cells, the MITF and BRN2 programs appear orthogonal, such that “BRN2 high” populations can contain both “MITF high” and “MITF low” cells." (PMID 41405996, 2025). "Our finding that DANCR is directly regulated by both MITF and c-MYC may explain its high expression in both proliferative (MITF-high) and invasive (c-MYC-high) transcriptional states in melanoma." (PMID 41336739, 2025). "MGNET typically shows positivity for S100 and SOX10 while being negative for melanocytic markers like HMB-45, Melan-A, and MiTF, which are usually present in melanoma and CCS." (PMID 40429661, 2025). "Moreover, SPEF inhibited the expression levels of key melanogenic proteins such as tyrosinase, TRP-1, TRP-2, and MITF by downregulating the phosphorylation levels of CREB and PKA in α-MSH-stimulated melanoma cells." (PMID 40003988, 2025). "Barcode group 2 uniquely expressed lipid metabolism genes, such as FASN and APOE, which contribute to melanoma resistance by promoting MAPK inhibitor resistance through reducing lipid poly-unsaturation and protecting MITF^low/AXLĥigh persister cells from ferroptosis, respectively." (PMID 41000875, 2025). "Collectively, these findings underscore how multiple miRNAs, acting individually or synergistically, significantly impact melanoma metastasis and invasion through their ability to modulate SOX10, MITF, and their mutual targets via direct and indirect mechanisms." (PMID 40458894, 2025). "Moreover, fisetin reduced the protein expression levels of MITF and tyrosinase in both human melanoma cells and α-MSH-stimulated melanoma cells." (PMID 41373883, 2025). "In neural crest, melanocyte, and melanoma cells, PAX3 was found to regulate MITF, NGN2, RET, SOSTDC1, MSX2, DCT, and TYRP1 genes, as well as genes expressed ubiquitously or widely (and including melanocytes), such as BCL-XL, CXCR4, FGFR4, HES1, MET, NF1, TGFb2, and WNT1." (PMID 40428399, 2025). "In line with previous studies that linked RAF and MEK/ERK activation to cytoplasmic retention and nuclear export of MITF in melanoma cells, respectively, we here demonstrate in MCs that MEK and ERK inhibition reverted the low nuclear MITF and melanin production in FN-exposed MCs." (PMID 40973828, 2025). "The increase in MITF levels, especially in PTX monotherapy and combination groups, was accompanied by macroscopic evidence of enhanced pigmentation in the tumors, suggesting a shift towards a more differentiated melanoma phenotype." (PMID 40806647, 2025). "Markers such as S-100, Sox-10, HMB-45, MITF, and MART-1 align with malignant melanoma." (PMID 40008002, 2025).